MUC1 (mucin 1, cell surface associated)
Diseases named in the same sentence as MUC1 in open-access papers (continued):
Sharing a sentence is not in itself a finding about the gene and the disease.
pancreatic cancer (continued). "The expression of MUC1 on pancreatic tumour tissues and cancer cell lines was performed by immunohistochemistry and further confirmed by confocal microscope and flow cytometry analysis on the cell surface." (PMID 15599383, 2004). "Our results clearly indicated that MUC1 is an effective tumour surface marker for targeting pancreatic carcinoma." (PMID 15599383, 2004). "Furthermore, bioinformatics and molecular biology techniques were integrated to validate the expression pattern of MUC1 in pancreatic cancer and its clinical relevance, thereby providing a theoretical foundation for the targeted design of the DC vaccine." (PMID 41607777, 2026). "Western blot was used to detect MUC1 expression in pancreatic cancer cell lines." (PMID 41607777, 2026). "Western blot further confirmed MUC1 expression in pancreatic cancer cell lines." (PMID 41607777, 2026). "Furthermore, bioinformatic analysis was performed to compare MUC1 expression between pancreatic cancer and normal tissues and its correlation with patient prognosis." (PMID 41607777, 2026). "Bioinformatics analysis revealed that MUC1 was markedly overexpressed in pancreatic cancer tissues, and this overexpression correlated with reduced overall survival in patients, aligning with prior reports implicating MUC1 in tumor immune evasion and microenvironmental regulation." (PMID 41607777, 2026). "MUC1 was overexpressed in approximately 90% of pancreatic cancer samples and cell lines." (PMID 40699746, 2025). "In pancreatic cancer, MUC1 may interact and regulate different components of the TME, supplying various processes such as neoangiogenesis, metastasis, immune evasion, and oncogenic signaling." (PMID 40001578, 2025). "For example, the crosstalk between MUC1 and HIF-1α signaling increases glycolytic flux, leading to increased pyrimidine synthesis in tumor cells, which competes with GEM, reducing its toxicity and causing chemoresistance in pancreatic cancer." (PMID 39990228, 2025). "In the serum of pancreatic cancer patients, MUC1 levels increase in a stage-dependent manner and so MUC1 expression may be potentially used as biomarker for the diagnosis and staging of PDAC patients." (PMID 40001578, 2025). "Notably, as a natural ligand for galactoglucan lectin-4, MUC1 induced EMT at the post-transcriptional level by modulating the expression of miRNAs in pancreatic cancer." (PMID 39857769, 2025). "Similarly, anti- mucin 1 (MUC1) CAR-NK cells exhibited potent suppression of pancreatic cancer progression in vivo, correlating with enhanced infiltration and reduced stromal barrier density." (PMID 41181137, 2025). "To identify whether HIF-1α mediates the regulatory mechanism governing MUC1-mediated regulation of SAT1, we assessed the expression of HIF-1α in MUC1-depleted pancreatic cancer cell lines." (PMID 38547055, 2024). "Notably, MUC-1 expression levels have been reported to be elevated in more than 60% of patients with pancreatic cancer, and the levels have been found to significantly correlate with tumor size." (PMID 38756774, 2024). "MUC1 also enhances the invasiveness of pancreatic cancer cells by inducing EMT, which may also contribute to the occurrence of PNI." (PMID 39061654, 2024). "Thus, we posited that MUC1 reprograms polyamine metabolism to regulate pathogenesis and therapy response in pancreatic cancer." (PMID 38547055, 2024). "further observed that in pancreatic cancer, MUC1 overexpression induces EMT, enhancing tumor cell invasion and metastasis through MUC1’s interaction with β-catenin, leading to its nuclear translocation and activation of genes associated with EMT and metastasis." (PMID 38361923, 2024). "Given our hypothesis that MUC1-mediated enhanced pancreatic cancer proliferation is mediated through SAT1, we treated MUC1-depleted cells with N1-acetylspermidine, the product of SAT1." (PMID 38547055, 2024). "As a result, MUC1 is directly related to chemotherapy resistance of pancreatic cancer cells." (PMID 38164273, 2024).
pancreatic cancer (continued). "To investigate this hypothesis, we investigated whether the expression of polyamine pathway genes correlated with MUC1 mRNA expression in pancreatic cancer patient dataset from the TCGA cohort." (PMID 38547055, 2024). "In another initial clinical trial that included patients with advanced pancreatic cancer, MUC-1 showed antigen-specific T-cell responses in 5 of 8 patients (62.5%) who could be evaluated." (PMID 38756774, 2024). "A Phase 1 trial involved 42 patients diagnosed with unresectable or recurrent pancreatic cancer who were vaccinated with MUC1-DCs—DCs transfected with MUC1-mRNA via electroporation—in conjunction with gemcitabine and MUC1-induced cytotoxic lymphocytes, MUC1-CTLs." (PMID 39329989, 2024). "Previous research has shown that the cytoplasmic tail of MUC1 physically interacts with and blocks the proteasomal degradation of HIF-1α in pancreatic cancer cell lines and animal models, and higher expression of MUC1 was observed in gemcitabine-resistant cells." (PMID 38540735, 2024). "Additionally, CAR T cells targeting hypoglycosylated MUC1 in hematological and pancreatic cancers showed encouraging results." (PMID 38611013, 2024). "According to certain theories, MUC1 has a function in the onset and spread of pancreatic cancer and may be an important marker for detection." (PMID 38540735, 2024). "The cancer-associated Tn glycoform of MUC1, a neoantigen that is present in a variety of cancers, was found to be a good candidate, and anti-Tn-MUC1 CAR T cells demonstrated target-specific cytotoxicity in xenograft models of pancreatic cancer." (PMID 37511431, 2023). "It has been shown that [177Lu]Lu-DOTA-C595 binds to MUC1-CE positive pancreatic cancer cells." (PMID 37578571, 2023). "Expression of MUC1-CE has also been linked with chemoresistance and disease progression, thus targeting of MUC1-CE positive pancreatic cancer cells could have value in treating advanced PDAC." (PMID 37578571, 2023). "It has a high binding affinity and specificity to tumor-associated MUC1, decreased binding to circulating MUC1 from colon and pancreatic cancer patients, and no binding to peripheral blood mononuclear cells (PBMCs)." (PMID 37489369, 2023). "We demonstrated that SN-131 is a promising antibody that exhibits specific and strong binding affinity with pancreatic cancer-relevant MUC1 TRDs carrying Tn and core 1 type O-glycans such as T and particularly ST antigens at the immunodominant Asp-Thr-Arg motif." (PMID 37547453, 2023). "Several studies have shown that MUC1-CE is expressed in over 90% of pancreatic cancers." (PMID 37578571, 2023). "Co-targeting MUC1 with gemcitabine can improve the therapeutic effect of pancreatic cancer." (PMID 35709153, 2022). "Importantly, we found that the conjugate of HzMUC1 and MMAE as ADC is very effective in killing MUC1 positive pancreatic cancer cells at low concentration." (PMID 36572921, 2022). "The overexpression of mucin 1 (MUC1) in pancreatic cancer cells also resulted in VSV resistance." (PMID 35686109, 2022). "However, the expression level of each MUC1 isoform on the surface of cancer cells is unclear, especially in pancreatic cancer." (PMID 36572921, 2022). "An open-label phase I study of advanced pancreatic cancer showed that recombinant prime-boost poxviruses (targeting MUC1 and carcinoembryonic antigen prolonged the overall survival of patients with anti-MUC1 and/or carcinoembryonic antigen-specific immune responses." (PMID 36224645, 2022). "Western blot and immunoprecipitation were used to detect MUC1 in pancreatic cancer cells." (PMID 36572921, 2022). "MUC1 can regulate glucose metabolism of pancreatic cancer through the HIF-1alpha pathway to induce resistance to gemcitabine, and targeted therapy for MUC1 may enhance the efficacy of gemcitabine for pancreatic cancer." (PMID 35709153, 2022).
pancreatic cancer (continued). "In addition, MUC1 expression can also reduce radiation-induced cytotoxicity and DNA damage in pancreatic cancer cells by enhancing glycolysis, pentose phosphate pathway, and nucleotide biosynthesis, thereby making tumors insensitive to radiotherapy." (PMID 35709153, 2022). "Interestingly, inhibition of O-glycosylation renders pancreatic cancers overexpressing the transmembrane mucin MUC1 more sensitive to 5-FU." (PMID 35131032, 2022). "High levels of TRS, as well as MUC1, were related to poor survival outcomes in pancreatic cancer." (PMID 36017335, 2022). "HzMUC1 antibody binds to MUC1 on the cell surface of pancreatic cancer cells." (PMID 36572921, 2022). "In addition, sEV carrying members of the EGFR, EpCAM, HER2, MUC1, and Wnt families are also highly sensitive and specific in the diagnosis of pancreatic cancer and can be used as early biomarkers." (PMID 34980146, 2022). "Our data show that HzMUC1-MMAE treatment could induce the G2/M cell cycle arrest and apoptosis in the MUC1 positive pancreatic cancer cells Capan-2 and CFPAC-1." (PMID 36572921, 2022). "More than 90% of pancreatic cancers have abnormally high expression of MUC1." (PMID 36572921, 2022). "In addition, confocal microscopy analysis of Capan-2 and CFPAC-1 cells clearly revealed that the HzMUC1 recognized MUC1 on the surface of pancreatic cancer cells." (PMID 36572921, 2022). "In this study, we utilized the fluorescence quenching and easy separation abilities of Fe3O4@DOP NPs, and a locked MUC1 molecular probe: aptamer-trigger (Apt-Tri) for assisting signal contrast enhancement in the detection of MUC1 overexpressed pancreatic cancer cells." (PMID 35197099, 2022). "MUC1 localization in pancreatic cancer cells was determined by confocal microscopy." (PMID 36572921, 2022). "Moreover, the system is universal because it can be used in detection or imaging of MUC1 overexpressed cancer cells, and the presented detection approach can open new avenues on Apt based recognition of other pancreatic cancer biomarkers." (PMID 35197099, 2022). "MUC1 is overexpressed in colon, breast, ovarian, lung, and pancreatic cancers." (PMID 35522218, 2022). "Therefore, developing a method that can profile or quantify the expression of MUC1 is promising in diagnosis or monitoring the treatment of pancreatic cancer." (PMID 35197099, 2022). "In addition to the study on the carcinogenic mechanism, researchers also found that the expression of MUC1 promoted the drug resistance of pancreatic cancer." (PMID 35709153, 2022). "Furthermore, as recently shown in murine pancreatic cancer cell lines MUC1 is a potential therapeutic target with small molecules in early clinical development, stimulating the characterization of a potential target population in pancreatic cancer." (PMID 34386419, 2021). "Comparison with transcriptomic signatures might further clarify the prognostic value of MUC1 in pancreatic cancer." (PMID 34386419, 2021). "The current review study identifies 22 IHC biomarkers as diagnostic tools for pancreatic cancer that embrace: Pentraxin-3, ENO1, REG4, POSTN, CA125, CA242, Galectin-1, Galectin-9, Maspin, pVHL, MUC1, MUC5AC, THBS2, LTBP2, CPA4, IMP3, CD13, Dkk1, KOC, S100P, Mesothelin, PAM4." (PMID 34988027, 2021). "MUC1 is widely used as tumor marker especially in breast, ovarian, lung and pancreatic cancer." (PMID 34386419, 2021). "Therapeutic strategies targeting KL-6/MUC1 glycosylation may therefore help to control the invasive behavior of pancreatic cancer cells." (PMID 34207342, 2021). "MUC1 also enhances the invasiveness of pancreatic cancer cells by inducing EMT." (PMID 34207342, 2021). "MUC1 overexpression also showed an association with increased glucose uptake, and with HIF-1α, GLUT1, and LDHA protein expression, in an orthotopic mouse model of pancreatic cancer." (PMID 34681277, 2021). "Many authors consider MUC1 as a valid target in pancreatic cancer treatment." (PMID 33921242, 2021).
pancreatic cancer (continued). "When adoptively transferred, MUC-1 specific T cells showed strong tumour cytotoxicity, providing a rationale for the use of adjuvant immunotherapy via adoptive cell transfer in the treatment of pancreatic cancer." (PMID 33920118, 2021). "We analyzed the infiltration of pancreatic cancer cells into pancreatic islets via double-immunolabeling of human pancreatic cancer tissues with insulin or glucagon and the pancreatic cancer cell marker cytokeratin 19 (CK-19) or Mucin-1 (MUC1)." (PMID 33440856, 2021). "COX2 has been shown to be regulated by mucin protein MUC1 in pancreatic cancer." (PMID 34070449, 2021). "MUC1 is an interesting target for antibody-based anti-cancer therapy, as it is expressed by a wide variety of tumors, including breast, ovarian, lung, colon, and pancreatic carcinomas as well as multiple myeloma." (PMID 34070311, 2021). "Significant efforts have been made to identify new pancreatic cancer-associated antigens, preferably shared by the majority of patients, such as carcinoembryonic antigen (CEA), mucin-1 (MUC-1) and the product of mutated KRAS, to develop targeted vaccination strategies." (PMID 35582441, 2020). "Though previous reports have suggested that MUC1, MUC4, and DNA-PKcs might enhance pancreatic cancer chemoresistance, the underlying mechanism remains largely unknown." (PMID 32123287, 2020). "Autologous PBMCs from resectable pancreatic cancer patients obtained either before surgery or during gemcitabine treatment, were cultured with MUC-1-expressing pancreatic cancer YPK-1 cells for 10 days and re-infused in the patients for a total of three rounds." (PMID 35582441, 2020). "Based on that, his team developed an anti-Tn-MUC1 CAR-T cell that recognized the cancer-specific cell surface expressing Tn-MUC1, and demonstrated the target-specific cytotoxicity and suppression of tumor growth in xenograft models of T cell leukemia and pancreatic cancer." (PMID 32194541, 2020). "Colon adenomas and IPMN express abnormal MUC1 found also in colon and pancreatic cancer." (PMID 31275327, 2019). "Additionally, KCM mice develop spontaneous tumors of the pancreas, with tumor cells expressing large amounts of hypo-glycosylated MUC1 as observed in human PDAs." (PMID 31114758, 2019). "MUC1 is a glycoprotein that is expressed in nearly all pancreatic cancers." (PMID 29946224, 2018). "Therefore, we conclude that the anti-hMUC1 antibody specifically targets MUC1 and suppresses its function in pancreatic cancer in vitro and in vivo and can be further developed as a promising targeted therapy to treat pancreatic cancer." (PMID 29987260, 2018). "We are thus interested in blocking MUC1′s role in pancreatic cancer." (PMID 29987260, 2018). "MUC1 may interact with other known growth factor receptors including EGF receptor (EGFR) to promote pancreatic cancer." (PMID 29987260, 2018). "From a mechanistic perspective, the unique ability of ILK to regulate MUC1-C stability, in conjunction with STAT3-activated MUC1 gene expression, upregulates MUC1-C and enables pancreatic cancer cells to interact with the tumor microenvironment to promote an aggressive phenotype." (PMID 28692035, 2017). "PDGF-A expression is regulated by mucin 1 (MUC1) during pancreatic cancer progression." (PMID 28986588, 2017). "Similarly, examination of pancreatic tumor cell lines derived from tumors of KPC mice that expressed or were null for MUC1 showed a modest increase in total c-Jun within the nucleus when MUC1 was expressed." (PMID 27220889, 2016). "In addition, upregulation of AGR2 promotes the expression of MUC1, which acts as an important regulator of the metabolism of pancreatic cancer cells." (PMID 27322206, 2016). "Furthermore, we demonstrated that MUC1 enhanced steady state ERK activation in pancreatic cancer cells, further supporting the link between ERK activation and the functional activity of MUC1 and FRA-1." (PMID 27220889, 2016).
pancreatic cancer (continued). "In the present study, we determined whether anti-MUC1 antibody conjugated with a fluorophore could target and visualize pancreatic cancer in vitro and in vivo models." (PMID 25815753, 2015). "In addition, fluorescence imaging targeted at MUC1 in pancreatic cancer can improve tumor visualization in order to achieve complete resection during surgery." (PMID 25815753, 2015). "MUC1 is overexpressed in over 90% of pancreatic cancer patient tumors." (PMID 25815753, 2015). "The results of all experiments showed that anti-MUC1 (CT2) antibody could detect MUC1 on the cell membrane of pancreatic cancer cells in vitro." (PMID 25815753, 2015). "This study showed that fluorophore conjugated anti-MUC1 antibodies could visualize pancreatic tumors in vitro and in vivo and may help to improve the diagnosis and treatment of pancreatic cancer." (PMID 25815753, 2015). "The goal of this study was to determine whether MUC1 antibody conjugated with a fluorophore could be used to visualize pancreatic cancer." (PMID 25815753, 2015). "One study, investigating the combination of MUC1-specific DC therapy in combination with MUC1-specific cytotoxic T lymphocyte ACT in 20 patients with advanced pancreatic cancer (APC) yielded a CR in one patient (5%), stable disease in 25% (5/20), a mean survival of 9.8 mo, and no grade 3–4 toxicity." (PMID 29546098, 2015). "Thus, evaluation of the DNA methylation status of MUC1 can provide important information for diagnosis of human pancreatic neoplasms." (PMID 24714692, 2014). "We retrospectively analyzed the outcome of 42 patients with unresectable or recurrent pancreatic cancer treated with MUC1-DCs (MUC1-mRNA transfected DCs) and MUC1-CTLs (lymphocytes stimulated by co-culture with a MUC1 expressing human pancreatic cancer cell line and IL-2)." (PMID 24947606, 2014). "In continuation of those investigations, this study also showed that inhibition of MUC1 in vivo could decrease tumor burden in mice, thereby confirming that the MUC1-HSP70 association is an essential factor in the survival of pancreatic cancer cells." (PMID 22912777, 2012). "Therefore this study indicates that MUC1-c interacted with HSP70 in the cytosol of pancreatic cancer cells and localized to the lysosomes in these cells." (PMID 22912777, 2012). "Pancreatic cancer tissues over-express MUC1 in 81% (43/53) of patient tumors." (PMID 24212784, 2011). "A vaccine composed of a 100 aa MUC1 peptide administered with SB-AS2 adjuvant (a mixture of MPL and QS-21 in an oil-in-water emulsion) to 16 patients with resected or locally advanced pancreatic cancer induced weak MUC1-specific humoral and T-cell responses in some patients." (PMID 24212946, 2011). "This is in contrast to previous findings in which MUC1 was shown to influence cell migration in breast, cervical, renal and pancreatic carcinoma cell lines and cell invasion in breast, lung, gastrointestinal, hepatic and pancreatic carcinoma cell lines." (PMID 22073229, 2011). "This indicates a potential clinical implication in the treatment of MUC1+ pancreatic cancer." (PMID 24281201, 2010). "MUC1-Siglec-4a binding promotes the perineural invasion of pancreatic cancer cells." (PMID 20497550, 2010). "Our data suggested that similar immunization strategies might be used in pancreatic cancer patients with over-expression of MUC1 for the treatment of early cancers or the eradication of minimal residual lesions." (PMID 19534821, 2009). "To investigate the protective and therapeutic effect of the DNA vaccine pcDNA3.1-VNTR against pancreatic cancer, we first constructed a murine pancreatic cancer cell which could express the human MUC1 protein and mainly on the cell membrane." (PMID 19534821, 2009). "Interestingly, suppression of MUC1 expression in a pancreatic cancer cell line reduced these cells' metastatic potential, and was accompanied by reduced MAL2 levels." (PMID 19175940, 2009).